CXCL12 (C-X-C motif chemokine ligand 12)
Diseases named in the same sentence as CXCL12 in open-access papers (continued):
Sharing a sentence is not in itself a finding about the gene and the disease.
cancer (continued). "CXCL12, a ligand for CXCR4, is abundantly produced by neighboring stromal cells and activation of CXCR4-expressing cancer cells by CXCL12 leads to enhanced chemotaxis, trans-endothelial migration, and invasion." (PMID 32224910, 2020). "CXCL-12, for instance, is an essential cytokine present in bone marrow leading to bone metastatic colonization of cancer cells." (PMID 32225005, 2020). "In cancer spreading, CXCR4 is the main cCKR, whose expression enables cancer cells to migrate and metastasize into the organs that secrete high levels of its ligand, CXCL12." (PMID 32456359, 2020). "CXCL12 can activate various signal pathways of cancer cells to promote proliferation, infiltration and angiogenesis and suppress apoptosis." (PMID 32972006, 2020). "In this review, we describe the roles of the CXCL12/CXCR4/CXCR7 axis in cancer progression and summarize strategies to develop novel targeted cancer therapies." (PMID 33363463, 2020). "In solid tumors, CXCL12 can be secreted both by cancer cells and CAFs, playing a role in paracrine or autocrine fashion, through either CXCR4 or CXCR7." (PMID 32784743, 2020). "In normal and cancer cells, CXCL12 activation induces release of calcium from internal stores, triggering phospholipase C activation and the generation of inositol trisphosphate and diacylglycerol." (PMID 33239060, 2020). "The CXC4/CXCL12 is a key axis in the acquisition of high motility and invasive properties in cancer cells." (PMID 32224910, 2020). "CXCL12 signaling has also been observed in CXCR4 expressing cancers and is involved in cancer cell invasion and metastasis." (PMID 32316469, 2020). "Other evidence suggests that CXCR4 mediates the interactions between cancer cells and stroma cells by combining with its natural ligand CXCL12." (PMID 32538273, 2020). "These cancer cells were prone to metastasize to the CXCL12-rich microenvironment of the bone marrow, suggesting that CAFs at primary sites educate cancer cells to metastasize to bone." (PMID 33050237, 2020). "Increasing evidence indicates a pivotal role for the CXCL12/CXCR4 axis in organ-specific metastasis of various cancers." (PMID 32079335, 2020). "CXCL12 has an important physiological role in diverse processes including embryonic development, inflammation, organogenesis, immune mediation, and cancer metastasis." (PMID 33092204, 2020). "Preclinical and clinical observations of high CXCR4 and CXCL12 expression levels in different tissues affected by cancer cell invasion highlight their importance as potential targets for delivery strategies with advanced therapies." (PMID 33233846, 2020). "A series of efforts has been undertaken to investigate the prominent role of the CXCL12/CXCR4 axis in cancer progression of different cancer entities including both histologic subtypes of EC." (PMID 32560537, 2020). "The abrogation of the CXCR4/CXCL12 axis results in reduced metastatic burden in a variety of mouse models of cancer." (PMID 32232002, 2020). "Here, we report the discovery of the geometry of the complex between full-length CXCR4, a prototypical CXC receptor and driver of cancer metastasis, and its endogenous ligand CXCL12." (PMID 32271748, 2020). "In this section, we describe the effects of CXCL12 on innate and adaptive immune cells in human cancers." (PMID 33096815, 2020). "Macrophages accelerate cancer growth through a CXCL12-potentiated GM-CSF/HB-EGF paracrine loop, leading to poor prognosis and shorter survival time in CRC patients." (PMID 32235004, 2020). "CXCR4/CXCL12 interaction triggers different downstream pathways in cancer cells or in several cells of TME, resulting in diverse biological responses, as angiogenesis, metastasis, proliferation and survival." (PMID 32784743, 2020). "We identify a crosstalk between CAF-S1 and cancer cells involving both CXCL12 and TGFβ, consistent with data showing that CAFs secrete CXCL12 and promote cancer cell migration." (PMID 31964880, 2020).
cancer (continued). "Cancer cells expressing CXCR4 tend to home to secondary organs where its ligand CXCL12 is actively secreted, mainly by mesenchymal stromal cells." (PMID 32432042, 2020). "In ZF, human cancer cells can sense host (ZF) CXCL-12, which is produced by mesenchymal stem cells in CHT, inducing metastatic colonization." (PMID 32225005, 2020). "While CAF-S1 stimulate cancer cell migration and initiate an epithelial-to-mesenchymal transition through CXCL12 and TGFβ pathways, highly contractile CAF-S4 induce cancer cell invasion in 3-dimensions via NOTCH signaling." (PMID 31964880, 2020). "In conclusion, CAF-S1 fibroblasts promote BC cell migration and EMT initiation in cancer cells in a CXCL12- and TGFβ-dependent manner." (PMID 31964880, 2020). "CXCR4, the receptor of the stromal cell-derived factor-1α (SDF-1α, also known as CXCL12) is one of the chemokines that has been researched extensively for its involvement in cancer metastasis and migration." (PMID 32630806, 2020). "Activation of CXCR4 receptor by CXCL12 has been reported in different cancers such as brain neoplasms, colorectal cancer, prostrate cancer, melanoma, ovarian cancer, etc." (PMID 33414786, 2020). "In conclusion, compounds A, B, and D can act as promising leads in the development of potent inhibitors against CXCL12 to reduce cancer metastasis." (PMID 33092204, 2020). "For example, CXCR4-positive cancer cells can be recruited to organs with high expression of CXCL12, including liver, lungs, and bone marrow." (PMID 33363463, 2020). "A particularly important role in chemotaxis is played by the chemokine receptor, CXCR4, and by its ligand, CXCL12 (also known as SDF1, stromal cell-derived factor, which initiate directed cell migration in various kinds of cancer." (PMID 32292657, 2020). "As CAF-S1 attract cancer cell at distance and secrete high levels of CXCL12, we first analyzed the impact of CXCL12 silencing in CAF-S1 and CAF-S4 on BC cell proliferation and migration." (PMID 31964880, 2020). "Bioinformatic analyses, performed to assess the role of 41 cytokines after RT exposure and their network interactions, suggested TGF-β, MIF, CCL2, CXCL5, CXCL8 and CXCL12 as master regulators of cancer immune escape in RMS tumors." (PMID 32854690, 2020). "CXCL12/CXCR4 interaction can also induce activation of the canonical Wnt pathway that plays a key role in iCCA growth, metastasis and cancer susceptibility." (PMID 32784743, 2020). "It has been suggested that CAFs promote angiogenesis by recruiting endothelial progenitor cells (EPCs) into carcinomas, which is mediated by CXCL12." (PMID 33363463, 2020). "Collectively, these findings revealed that in response to CXCL12/CXCR4 activation, miR-133a-3p was repressed and implicated with cancer cell motility by upregulating RhoA through direct binding to RhoA 3’UTR." (PMID 30678736, 2019). "CXCR4 expression is deregulated in 23 cancers and has been shown to increase cancer cell metastasis toward CXCL12 expressing cells (Balkwill, 2004a,b)." (PMID 31139626, 2019). "CXCL12 and its specifc receptors CXCR4 have been shown to be associated with the growth and metastasis of a variety of malignant tumors." (PMID 31500630, 2019). "The CXCL12 gene is directly targeted by miR-126 and miR-126* and results in the suppression of the CC-motif chemokine ligand 2 (CCl2) produced by cancer cells in a CXCL12-dependent manner." (PMID 31683635, 2019). "Another interesting observation was that the unmodified alginate samples contained CXCL1, CXCL2, CXCL12, which are powerful neutrophil chemoattractants that are involved in many immune responses including wound healing, cancer metastasis, and angiogenesis." (PMID 31748525, 2019). "First of all, the CXCL12/CXCR4 interaction is critical for the recruitment of metastatic cancer cells into the bone marrow niche, since these cells, by expressing CXCR4, essentially hijack the homing mechanism for hematopoietic cells." (PMID 31572390, 2019).
cancer (continued). "Targeting CXCL12 or CXCL12 receptor CXCR4 has a synergistic effect with anti‐PD‐L1 treatment; the combined treatment caused T cell accumulation and cancer regression." (PMID 31365790, 2019). "It is therefore likely that the increased co-expression of CXCR4 and CCR5 in RhoA knockdown cancer cells facilitates the recruitment of CXCL12/CCL5 secreting CAFs and later the TAMs into the TME." (PMID 31705019, 2019). "The reduced RhoA activity resulted in increased expression of the cognate receptor, CXCR4, for CXCL12 in 4T1 cancer cells." (PMID 31705019, 2019). "These DCs produce CXCL12 themselves, representing a potential feed-forward mechanism where tolerant DCs recruited by cancer stem cells also maintain their stemness." (PMID 31921140, 2019). "HSC driving factors such as osteoblast secreted stromal cell-derived factor 1 (SDF-1/CXCL12) binds to CXCR4 on cancer cells and retains them in the HSC niche." (PMID 31447846, 2019). "Several cytokines were identified, including IL-6, IL-8, IGF1, IGF2, and CXCL12, all of which promoted survival of cancer cells." (PMID 31014370, 2019). "It is established that cancer cells expressing CXCR4 home to secondary organs where CXCL12 is highly secreted, mainly by mesenchymal stromal cells." (PMID 30787324, 2019). "Activation of CXCL12/CXCR4 axis has been found to be associated with invasion and metastasis in many cancers." (PMID 30678736, 2019). "These cells can secrete a variety of cytokines promoting cancer stemness through NF-κB pathway, such as CXCL12, IL6 and IL8." (PMID 30510501, 2018). "Consistent with the important roles of CXCL12/CXCR4 in cancer, many studies have proven that high levels of CXCL12 and CXCR4 are related to worse prognosis in various malignant tumors." (PMID 30574021, 2018). "Again, apart from autocrine/paracrine TGFβ and stromal cell-derived factor-1 (SDF-1 or CXCL12) signaling, ECM stiffness plays an important role in differentiation of stromal fibroblasts into cancer associated fibroblasts (CAFs)." (PMID 30128085, 2018). "Cancer cells induce TGF-β-dependent upregulation of CXCR4 in monocytes, while CXCL12 expressed by perivascular fibroblasts attracts these motile TAMs toward the blood vessels, bringing motile cancer cells with them." (PMID 29719241, 2018). "Since the CXCR4/CXCL12 axis has been established to play an important role in the homing of cancer cells to the bone, the effect of PTH inhibition of CXCL12 secretion by MC3T3-E1 cells (preosteoblasts) was confirmed." (PMID 30151009, 2018). "CXCL12 and its specific receptors CXCR4 have been shown to be associated with the growth and metastasis of a variety of malignant tumors." (PMID 29305742, 2018). "CXCL12 downregulation affected HSPCs migration towards MSC/cancer cells co-culture or conditioned medium." (PMID 29760166, 2018). "High expression of the serum response factor in stromal fibroblasts induces cancer cell metastasis by CXCL12/CXCR4 signaling." (PMID 29883428, 2018). "The CXCL12/CXCR4/ACKR3 axis is frequently hijacked by cancer cells to promote their survival, growth, resistance to chemotherapy, metastasis and immune evasion." (PMID 30257500, 2018). "The chemotactic properties of CXCR4 combined with its ability to activate pro-survival mechanisms and stimulate cellular proliferation places the CXCR4/CXCL12 axis at the vanguard of metastasis and tumorigenesis for many cancers." (PMID 29682200, 2018). "In our study, among the selected genes related to the partial processes of cancer cell invasivity, we identified higher cancer-specific methylation levels in the CXCL12, TWIST1 and SNAI2 genes." (PMID 30189837, 2018). "Among cytokines, chemokines CXCL14, and CXCL12 play an important role in paracrine cross‐talk between fibroblasts and cancer cells." (PMID 29380537, 2018). "CXCL12 and its receptor CXCR4 were implicated in cancer cell migration, invasion, and metastasis through formation of chemotactic gradients." (PMID 29596520, 2018).
cancer (continued). "Numerous clinical studies proved the effectiveness of plerixafor (AMD3100), a CXCR-4 inhibitor as well as CTCE-9908, a CXCL-12 peptide analogue, in cancer treatment." (PMID 28660349, 2018). "Several of these pro-inflammatory chemokines such as CXCL1, CXCL8 and CXCL12 drive cancer progression by facilitating cell growth, survival and migration and inducing angiogenesis." (PMID 29719625, 2018). "We found that CXCL12 – CXCR4 signaling induces sensitivity of the cancer cells to specific molecular inhibitors of MAPK and PI3K pathways, preventing proliferation of TNBC cells." (PMID 29416611, 2018). "Recent studies have proved that the CXCR-4 and its ligand CXCL-12 (SDF-1) are promising targets for cancer therapy." (PMID 28660349, 2018). "Pre-clinical models in chronic lymphocytic leukemia (CLL) also showed that NOX-A12 effectively prevented chemotaxis of cancer cells towards CXCL12 and sensitized the cells to chemotherapies in bone marrow stem cell (BMSC) co-cultures." (PMID 29562664, 2018). "Migration and invasion of CXCR4+ papillary thyroid carcinoma cells are dependent on CXCL12, which was produced by senescent cancer cells at the invasive border." (PMID 29527513, 2018). "During hypoxia and upon angiogenic factor stimulation, CXCL12 can be secreted by specialized stromal cells, thus exerting multiple effects on both cancer and endothelial cells." (PMID 30591657, 2018). "The role of CXCL12/CXCR4 in cancer cell trafficking to bone has been explored extensively; however, there is a potential function for this pathway in modulating OCLs and bone resorption." (PMID 29930538, 2018). "This was shown for triple-negative breast cancer that responds to IGF/CXCL12-secreting CAFs by increasing the proportion of Src kinase-hyperactive cancer cells with disseminating potential." (PMID 29774124, 2018). "The chemokine receptor, CXCR4 is expressed in over 30 types of malignant tumors and, through interaction with its ligand CXCL12, was shown exert pleotropic pro-tumorigenic effects." (PMID 30257500, 2018). "In response to the induction of remote tissue injury, i.e. induction of ischemia, as found in many cancers, we observed members of the miR-25-93-106b cluster to be strongly upregulated resulting in downregulation of CXCL12 in the BM stromal niche." (PMID 28423491, 2017). "CXCL12/CXCR4 is known to regulate the critical steps of cancer invasion and metastasis; therefore, EC cells with increased CXCR4 expression have a high metastatic ability." (PMID 29383153, 2017). "Although several chemokines, such as CCL4, CCL19, CCL21, CXCL2 or CXCL12, were upregulated at the invasive border than cancer centre, expressions of their receptors were very low in PTC, except for CXCL12 receptor." (PMID 28489070, 2017). "Then we can draw that TAMs in malignant tumors tend to M2 subtype possibly through CXCL12/CXCR4/JAK2/STAT3 signaling pathway." (PMID 28630636, 2017). "The BM stromal niche plays a crucial role for survival, maintenance, and mobilization of stem and progenitor cells as well as cancer (stem) cells via the production of chemoattractsignals such as CXCL12." (PMID 28423491, 2017). "In recent years, research has shown an association between CXCL12/CXCR4 signalling and cancer progression." (PMID 29225688, 2017). "CXCL12 has been reported to be overexpressed in various cancer types which, in turn, strongly promotes proliferation, migration and invasion." (PMID 28445977, 2017). "Characteristic fibroblast activation gene targets such as ACTA2, COL1A1 and TNC were significantly upregulated in CAFs together with typical cancer-induced chemokines most prominently CXCL12, which has been reported for this cell line." (PMID 28372546, 2017).
cancer (continued). "The results demonstrated that human miR-125b, which positively regulates EMT and wnt/β-catenin signaling by targeting APC expression, is controlled by CXCL12/CXCR4 signaling in cancer cells." (PMID 28176874, 2017). "As we learn more about the molecular-, cellular-, and tissue-scale mechanisms that drive the formation of CXCL12 gradients and presumably cancer metastasis, we will be more equipped to disrupt the process." (PMID 29117251, 2017). "In our analysis, the expression of the potential tumor suppressor chemokine ligand 12 (CXCL12) was found to be decreased, possibly due to high methylation, in four different cancer types." (PMID 28178311, 2017). "CXCL12 is a key attraction and retention signal for stem cells including cancer stem cells via activation of its receptor CXCR4." (PMID 28423491, 2017). "The high affinity scFvs bound to receptor CXCR4 and inhibited its ligand, CXCL12, which resulted in cancer cell inhibition." (PMID 28491282, 2017). "CXCL12 is the most important CXC chemokine and is implicated in cancer cell extravasation and metastasis." (PMID 29112161, 2017). "The binding of CXCL12 to CXCR4 has been reported to play important roles in cancer growth, invasion and metastasis." (PMID 28489887, 2017). "Chemokine CXCL12 gradients drive chemotaxis in a CXCR4-dependent mechanism and have been implicated in cancer metastasis." (PMID 29117251, 2017). "The increased expression of CXCL12 in signal transduction pathway play a significant role in cancer progression through PI3k and Akt signaling." (PMID 28929029, 2017). "Anti-CXCR4 antibodies have been shown to inhibit CXCL12 mediated cancer cell adhesion, migration, and proliferation." (PMID 28890883, 2017). "Interruption of the CXCL12/CXCR4 axis using CXCR4 inhibitor AMD3100 or neutralizing CXCR4 antibodies blocked the progression of cancer metastasis." (PMID 28176874, 2017). "Outside the context of cancer, reduction of CXCL12 has potential significance in the field of autoimmune disorders, as neutralization of chemokines is thought to have a restraining effect on the autoimmune response." (PMID 28055968, 2017). "When CXCL12 in senescent cells was knocked down by shRNA, the invasion of cancer cells was markedly decreased." (PMID 28489070, 2017). "The peritoneum can attract CXCR4‐positive cancer cells to migrate toward and seed on through a CXCL12 gradient secreted by mesothelial cells." (PMID 28544785, 2017). "Expressed by stromal cells of distant organs, CXCL12 promotes metastasis by attracting cancer cells and stimulating cancer cell extravasation, migration, and adhesion to ECM and to stromal cells." (PMID 29112161, 2017). "During inflammation, the Cxcl12/Cxcr4 niche expands and supports cancer cell growth by paracrine release of growth factors such as Wnt5a." (PMID 29340033, 2017). "In fact, it is difficult to fathom how cancer cells use chemokine gradients to intravasate into blood vessels if endothelial CXCR7 is present to scavenge CXCL12." (PMID 29117251, 2017). "To rule out the possibility that other cytokines were involved in cancer cell migration, we created two kinds of CXCL12 knockdown senescent cells by shRNA or application of the AMD3100 which is well known CXCR4 antagonist." (PMID 28489070, 2017). "Here, the authors show that senescent cancer cells are localized at the invasive front in human papillary thyroid carcinoma, and that senescent cancer cells drive collective invasion via CXCL12 in mouse models." (PMID 28489070, 2017). "Binding of CXCR4 to CXCL12 is also proposed to play a role in cancer metastases, and CXCR4 antagonists are under study in human clinical trials for solid and non-solid tumors." (PMID 27005825, 2016). "High amounts of CXCL12 are produced by organs commonly affected by cancer metastasis, such as lung and liver." (PMID 27175473, 2016). "It will be worth determining if KLF8-high cancer cells tend to colonize in these other CXCL12-high tissues in addition to the lungs." (PMID 26993780, 2016).